SIK1 (salt inducible kinase 1)
Diseases named in the same sentence as SIK1 in open-access papers (continued):
Sharing a sentence is not in itself a finding about the gene and the disease.
Breast tumour (1 paper, 2019). "An in silico study confirmed that SIK1 expression was reduced in breast primary and metastatic breast tumours, as compared with normal tissues." (PMID 31819138, 2019). "Breast tumour biopsies obtained from the Tours University Hospital were analysed to assess SIK1 expression in the different breast tumour subtypes." (PMID 31819138, 2019). "This lower expression of SIK1 gene in breast tumours, compared to normal mammary tissues, was observed at all tumour stages." (PMID 31819138, 2019).
cocaine addiction (1 paper, 2017). "It has been shown that Sik1 plays a key role in cocaine addiction, which also shares a mechanism associated with ΔFosB upregulation." (PMID 28337120, 2017).
cognitive decline (1 paper, 2024). "A recent report indicates SIK1 downregulates synaptic α-amino-3-hydroxy-5-methyl-4-isoxazolepropionic acid (AMPA) receptors and contributes to cognitive decline in AD." (PMID 39605035, 2024).
COVID-19 (1 paper, 2023). A disease caused by infection with severe acute respiratory syndrome coronavirus 2. "Differential gene expression analysis in B cells and plasmablasts between patients with COVID-19 and HIV-1, relative to healthy controls revealed a common upregulation of SIK1, a gene that regulates cell cycling and plays a role in plasmablast maturation." (PMID 36992700, 2023).
developmental and epileptic encephalopathy (1 paper, 2022). An epilepsy associated with developmental impairment that may be due to either the underlying etiology or the superimposed epileptic activity, or both. "Six mutations in the salt-inducible kinase 1 (SIK1) have been identified in developmental and epileptic encephalopathy (DEE-30) patients, and two of the mutations are nonsense mutations that truncate the C-terminal region of SIK1." (PMID 35887274, 2022).
ependymal tumor (1 paper, 2020). A group of neoplasms which arise from the ependymal lining of the cerebral ventricles and from the remnants of the central canal of the spinal cord.
Epileptic spasm (1 paper, 2024). A sudden flexion, extension, or mixed extension-flexion of predominantly proximal and truncal muscles that is usually more sustained than a myoclonic movement but not as sustained as a tonic seizure. "Recent animal experiments have shown that SIK1 deficiency renders ACTH treatment ineffective in NMDA-induced epileptic spasms." (PMID 38070098, 2024).
Ewing sarcoma (1 paper, 2022). A small round cell tumor that lacks morphologic, immunohistochemical, and electron microscopic evidence of neuroectodermal differentiation. "To determine the role of SIK1 in DSRCT, we depleted SIK1 in JN, BER, and A673 cells, an Ewing Sarcoma cell line, with two independent siRNAs against EWSR1-WT1, SIK1, or a scramble siRNA." (PMID 35443736, 2022).
glioblastoma (1 paper, 2021). The most malignant astrocytic tumor (WHO grade IV).
heart failure (1 paper, 2025). Inability of the heart to pump blood at an adequate rate to meet tissue metabolic requirements. "The phosphorylation of HDAC7 by salt-inducible kinase 1 (SIK1), a member of the CaMK family, stabilizes the deacetylase, leading to an increase in c-Myc expression, which in turn promotes the progression of heart failure." (PMID 40710369, 2025).
Hypercalcemia (1 paper, 2023). An abnormally increased calcium concentration in the blood. "Ubiquitous/inducible SIK1/SIK2/SIK3 deletion caused modest increases in trabecular bone mass, with dramatic 1,25-vitamin D–mediated hypercalcemia." (PMID 36862513, 2023).
infantile spasms (1 paper, 2022). A rare epilepsy syndrome characterized by onset of epileptic spasms in infants between 2 and 12 months of age, and rarely up to 24 months. "To assess the relevance of the SIK1-MT to the pathophysiology of infantile spasms, we applied provocative drugs to induce seizures in SIK1-MT mice." (PMID 35887274, 2022). "Truncations of the SIK1 gene in two patients with infantile spasms occurred within a nuclear localization domain (NLD) in the C-terminal region." (PMID 35887274, 2022). "As suggested in human clinical research, our data support the hypothesis that the SIK1 gene is closely associated with epileptic seizures and raise the notion that SIK1 may be involved in the molecular pathway underlying the ACTH therapy for infantile spasms." (PMID 35887274, 2022). "In addition, considering the role of SIK1 in ACTH signaling, it would be intriguing to investigate the effect of ACTH on SIK1-MT mice because ACTH is the first-line drug for infantile spasms." (PMID 35887274, 2022). "Two out of six patients had nonsense mutations, resulting in the truncation of the C-terminal of the SIK1 protein and display infantile spasms and developmental abnormalities, including absent speech, repetitive behaviors, and poor social interactions." (PMID 35887274, 2022).
Miscarriage (1 paper, 2020). A pregnancy that ends at a stage in which the fetus is incapable of surviving on its own, defined as the spontaneous loss of a fetus before the 22th week of pregnancy. "Mapping of potential candidate genes at associated loci identified several genes (FGF9, TLE1, TLE4, E2F8, SIK1) with a plausible biological role in placental biology and miscarriage etiopathogenesis." (PMID 33239672, 2020).
Obesity (1 paper, 2017). Accumulation of substantial excess body fat. "Considering the low expression level of SIK1 in human adipose tissue, we are not sure of the physiological relevance of the differential expression of this isoform in obesity." (PMID 27807598, 2017).
osteoporosis (1 paper, 2019). A condition of reduced bone mass, with decreased cortical thickness and a decrease in the number and size of the trabeculae of cancellous bone (but normal chemical composition), resulting in increased fracture incidence. "Therefore, SIK1 inhibition is worth as a bone anabolic strategy for the treatment pathogenic conditions like osteoporosis and bone fracture." (PMID 31672960, 2019).
osteosarcoma (1 paper, 2022). A usually aggressive malignant bone-forming mesenchymal neoplasm, predominantly affecting adolescents and young adults. "SIK1 mRNA expression in osteosarcoma cells was detected by quantitative real-time reverse transcription PCR (qPCR)." (PMID 35346195, 2022).
pancreatic adenocarcinoma (1 paper, 2014). "By genome wide gene expression profiling we found that gastrin induces transcription of Salt-inducible kinase 1 (Sik1/Snf1lk) in the pancreatic adenocarcinoma cell line AR42J." (PMID 25384047, 2014).
psoriasis (1 paper, 2025). An autoimmune condition characterized by red, well-delineated plaques with silvery scales that are usually on the extensor surfaces and scalp. "We demonstrate the association between SIK1 and psoriasis, in which SIK1 expression is upregulated in keratinocytes for IMQ-induced psoriasis." (PMID 39959414, 2025). "Though we have described the role of SIK1 in IMQ-induced psoriasis, the mechanisms underlying the function of SIK1 for psoriasis are still poorly understood." (PMID 39959414, 2025). "Further work needs to be down to clarify the function of SIK1 in psoriasis with SIK1 deficiency mice." (PMID 39959414, 2025). "Western blot analysis of the SIK1 protein levels consistently showed increased expression in psoriasis." (PMID 39959414, 2025). "Inhibition of SIK1 kinase activity using a small molecular inhibitor (HG-9-91-01 or YKL-06-062) dramatically alleviated IMQ-induced psoriasis." (PMID 39959414, 2025). "In this study, using small molecular inhibitor HG-9-91-01 and YKL-06-062, we identify SIK1 as a critical regulator of IL17 signaling in psoriasis." (PMID 39959414, 2025). "Here, we found that salt-inducible kinase 1 (SIK1) was upregulated in the imiquimod (IMQ)-induced psoriasis mouse model." (PMID 39959414, 2025). "Our data showed that SIK1 was upregulated in IMQ-induced psoriasis, but SIK2 and SIK3 showed similar expression compared with control mice." (PMID 39959414, 2025). "Here, we identify that SIK1 is specifically upregulated in the imiquimod (IMQ)-induced psoriasis mouse model." (PMID 39959414, 2025). "To evaluate the roles of SIK1 in psoriasis, we established an IMQ-induced psoriasis-like mouse model and applied SIK1 inhibitor HG-9-91-01 to inhibit SIK1 kinase activity." (PMID 39959414, 2025). "Collectively, further work needs to clarify the underlying mechanisms by which SIK1 regulates IL17 signaling and the role of SIK1 in the pathogenesis of psoriasis." (PMID 39959414, 2025). "Perhaps the psoriasis phenotypes can be more moderated by topical treatment with SIK1 inhibitors HG-9-91-01 or YKL-06-062." (PMID 39959414, 2025). "In our study, we identify that IL17 induces SIK1 expression in keratinocytes, which is responsible for more expression of SIK1 in IMQ-induced psoriasis." (PMID 39959414, 2025). "Collectively, these results indicate that IL17 promotes SIK1 expression of keratinocytes in IMQ-induced psoriasis-like mouse models." (PMID 39959414, 2025). "Otherwise, our results provide evidence of the SIK1 kinase activity in psoriasis that inhibition of SIK1 alleviates pathologies of psoriasis." (PMID 39959414, 2025). "Collectively, our data identify SIK1 as a critical regulator in IL17 signaling and reveal an important role for SIK1 in psoriasis pathogenesis." (PMID 39959414, 2025). "Considering psoriasis mice express higher levels of SIK1, we ask whether SIK1 participates in the process of psoriasis." (PMID 39959414, 2025). "Thus, our study indicates that targeting SIK1 with small molecular inhibitors serves as a potential therapy for the treatment of psoriasis." (PMID 39959414, 2025). "In addition to psoriasis, SIK1 inhibitors HG-9-91-01 and YKL-06-062 were applied to induce melanin production in human and mouse skin, potentially impacting UV protection and skin cancer risk." (PMID 39959414, 2025). "Thus, inhibition of SIK1 presents a potential new therapeutic target for psoriasis." (PMID 39959414, 2025). "However, there are some limitations of therapy targeting SIK1 to treat psoriasis." (PMID 39959414, 2025). "To further confirm the effect of SIK1 on IMQ-induced psoriasis, we employed another SIK inhibitor, YKL-06-062, which also showed a high inhibitory effect on SIK1 compared with HG-9-91-01." (PMID 39959414, 2025). "Our results reveal that SIK1 participates to promote IL17-induced signaling through enhancing activation of NF-κB and MAPKs and exacerbates psoriasis-like skin inflammation." (PMID 39959414, 2025).
psoriasis (continued). "Our data reveal the therapeutic potential of SIK1 inhibitors HG-9-91-01 and YKL-06-062 for psoriasis, which significantly reduce skin inflammation of psoriasis." (PMID 39959414, 2025). "Collectively, our results reveal that SIK1 participates to promote IL17-induced signaling through enhancing activation of NF-κB and MAPKs and exacerbates psoriasis-like skin inflammation." (PMID 39959414, 2025). "Therefore, it is further need to assess the change of SIK1 phosphorylation in IL17-stimulated keratinocytes and psoriasis tissues." (PMID 39959414, 2025). "In addition, we performed the immunostaining using specific anti-SIK1 antibodies and found that IMQ-induced psoriasis skin showed increased levels of SIK1 in keratinocytes compared with control." (PMID 39959414, 2025). "Targeting SIK1 kinase activity with HG-9-91-01 and YKL-061 alleviates IMQ-induced psoriasis." (PMID 39959414, 2025).
renal fibrosis (1 paper, 2021). A final common manifestation of a wide variety of chronic kidney diseases characterized by glomerulosclerosis and tubulointerstitial fibrosis. "Mechanistically, we demonstrated that SIK1 mediated AA-induced AKI-CKD transition by regulating WNT/β-catenin signaling, the canonical pathway involved in EMT, inflammation and renal fibrosis." (PMID 33588892, 2021). "Thus, we speculate that SIK1 might be involved in the progression of AKI-CKD transition, which is characterized with EMT, inflammation and renal fibrosis." (PMID 33588892, 2021). "Thus, in this study, we aimed to elucidate the role and mechanism of SIK1 in AKI-CKD transition, which will provide a new therapeutic target for clinical prevention and treatment of renal fibrosis and will provide a new way to delay the progress of AKI-CKD transition." (PMID 33588892, 2021).
sarcoma (1 paper, 2022). A usually aggressive malignant neoplasm of the soft tissue or bone. "Expression of SIK1 was the highest in DSRCT compared to other sarcomas, while expression levels of SIK2, SIK3 and LKB1 in DSRCT were similar to other sarcomas." (PMID 35443736, 2022).
schizophrenia (1 paper, 2023). A major psychotic disorder characterized by abnormalities in the perception or expression of reality. "Therefore, an in-depth study is required to further verify the involvement of the SIK1/CRTC2/CREB1 signaling pathway in schizophrenia." (PMID 36744005, 2023). "In addition, two possible downstream pathways of miR-25-3p, including the SIK1/CRTC2/CREB1 and TWIST1/PI3K/Akt/GSK3β signaling pathways, were examined with the schizophrenic rat model to explore their potential associations with schizophrenia." (PMID 36744005, 2023). "In conclusion, this study suggests that altered SIK1/CRTC2/CREB1 and TWIST1/PI3K/Akt/GSK3β signaling pathways mediated by miR-25-3p is very likely to be associated with schizophrenia, revealing potential targets for the treatment and clinical diagnosis of schizophrenia." (PMID 36744005, 2023). "Since it was previously reported that CRTC1 is expressed almost exclusively in the hypothalamus and CRTC3 is expressed in adipose tissue, the SIK1/CRTC2/CREB1 signaling pathway was selected and its involvement in the pathophysiology of schizophrenia was investigated in this study." (PMID 36744005, 2023). "This study investigated whether miR-25-3p-mediated SIK1/CRTC2/CREB1 and TWIST1/PI3K/Akt/GSK3β signaling pathways are present in an animal model relevant to schizophrenia." (PMID 36744005, 2023). "In conclusion, the present study suggests that miR-25-3p-mediated SIK1/CRTC2/CREB1 and TWIST1/PI3K/Akt/GSK3β signaling pathways could be potential therapeutic targets for future antipsychotic drugs and candidate diagnosis biomarkers of schizophrenia." (PMID 36744005, 2023).
Stroke (1 paper, 2021). Sudden impairment of blood flow to a part of the brain due to occlusion or rupture of an artery to the brain. "Excessive expression of SIK1 in stroke lesion of HSD mice revealed the salinized microenvironment encountered by the infiltrated macrophages." (PMID 33845849, 2021).
thyroid cancer (1 paper, 2022). "All the data collectively supported that the anti-oncogenic capacity of LKB1 in thyroid cancer was mediated by the positive regulation of SIK1." (PMID 35912012, 2022). "Consistent with the previous studies, LKB1 was found to positively regulate SIK1 in thyroid cancer TPC-1 and BCPAP cells." (PMID 35912012, 2022). "We found that the expression of SIK1 was significantly lower in thyroid cancer tissues than that in normal tissues." (PMID 35912012, 2022). "Taken together, the results of the present study revealed, for the first time, that LKB1 could inhibit proliferation, metastasis phenotype and angiogenesis, and reverse EMT in thyroid cancer in vitro and vivo via the upregulation of SIK1." (PMID 35912012, 2022). "Moreover, the mRNA level of SIK1 was positively correlated with E-Ca level, and overexpression of LKB1 could upregulate p-SIK1 and SIK1 protein levels in thyroid cancer TPC-1 and BCPAP cells." (PMID 35912012, 2022).
virus infection (1 paper, 2025). "Further in vitro and in vivo experiments confirmed that SIK1 was up-regulated in virus infection, and it exerted antiviral effects in various viral infections." (PMID 41674661, 2025).